EN2 (engrailed homeobox 2)
Tractability: No criterion of Open Targets' tractability assessment is met for any kind of drug.
Gene: Protein-coding gene on chromosome 7 (155,458,129 to 155,464,831, forward strand). Ensembl gene ENSG00000164778.
Subcellular location: Nucleus
Subcellular location (Human Protein Atlas): Nucleoplasm; Nucleoli; Nucleoli fibrillar center
Gene Ontology:
Molecular function: sequence-specific double-stranded DNA binding; DNA-binding transcription activator activity, RNA polymerase II-specific; DNA-binding transcription factor activity, RNA polymerase II-specific; RNA polymerase II cis-regulatory region sequence-specific DNA binding; RNA polymerase II-specific DNA-binding transcription factor binding; transcription corepressor activity; DNA binding
Biological process: negative regulation of transcription by RNA polymerase II; neuron differentiation; positive regulation of transcription by RNA polymerase II; regulation of transcription by RNA polymerase II; embryonic brain development; negative regulation of neuron apoptotic process; regulation of DNA-templated transcription
Cellular component: fibrillar center; nucleolus; nucleoplasm; chromatin; nucleus
Genetic constraint (gnomAD): Loss-of-function variants: 6 observed, 15.29 expected, observed/expected ratio (o/e) 0.39, 90% interval 0.21 to 0.77. The synonymous counts are far from expectation, so gnomAD's model fits this gene poorly and the ratio says little. Missense variants: 510 observed, 384.06 expected, observed/expected ratio (o/e) 1.33, 90% interval 1.23 to 1.43. Synonymous variants: 270 observed, 186.68 expected, observed/expected ratio (o/e) 1.45, 90% interval 1.31 to 1.6.
Gene-disease validity (ClinGen):
ClinGen rates the evidence that EN2 causes each of these diseases.
complex neurodevelopmental disorder (autosomal dominant): Disputed. A disorder that involves more than one phenotype associated with the central nervous system, including but not limited to intellectual disability, autism, and seizures (epilepsy).
Homologues: Orthologues: chimpanzee EN2 (100% identical), macaque EN2 (98% identical), pig EN2 (94% identical), dog EN2 (92% identical), guinea pig EN2 (89% identical), mouse En2 (87% identical), rat En2 (86% identical), tropical clawed frog en2 (54% identical), zebrafish en2b (53% identical), zebrafish en2a (51% identical), rabbit EN2 (50% identical). Paralogues in human: EN1 (47% identical), CPHXL (10% identical), CPHXL2 (9% identical).
Diseases named in the same sentence as EN2 in open-access papers:
EN2 is named in the same sentence as 63 diseases in open-access papers, as found by Europe PMC text mining. Sharing a sentence is not in itself a finding about the gene and the disease. The quoted sentences say what the papers report.
autism (31 papers, 2010 to 2024). Persistent deficits in social interaction and communication and interaction as well as a markedly restricted repertoire of activity and interest as well as repetitive patterns of behavior. "En2 plays an important role in the development of the brain, especially the cerebellum, and was found to be associated with infantile autism." (PMID 36007075, 2022). "In this context, several genes downregulated in the brainstem of Hoxa5 cKO mouse at P21, such as Grm4, Cbln1, En2, Camk4, and Cadps2, have been associated to autism traits either in humans or in mouse models." (PMID 29187810, 2017). "It is intriguing that yet another autism-associated gene, in this case EN2, implicates disordered Akt-mTOR-S6K signaling in the disease phenotype." (PMID 24507165, 2014). "Our current studies aimed to define the function of one autism-associated gene, EN2, at a specific time during postnatal brain development." (PMID 24507165, 2014). "Other features shared between the En2 KO mice and people with autism are deficiencies in the number of deep nuclear, granule, and inferior olive neurons." (PMID 24151553, 2013). "Purkinje cells from the LF7GFP strain express GFP (green fluorescent protein), while the engrailed gene EN2 is associated with autism, and is known to cause morphological alterations at the cerebellar level." (PMID 23420185, 2013). "Our results demonstrate that En2 deletion in mice reduces social behaviors on several corroborative tasks relevant to the first diagnostic symptom of autism." (PMID 22829897, 2012). "Given the association between EN2 mutations and autism, we evaluated a wide range of behavioral phenotypes relevant to the diagnostic and associated symptoms of ASD, along with control measures." (PMID 22829897, 2012). "Remarkably, a study in Han Chinese autism cases confirmed EN2 as a susceptibility gene, but found the A-C haplotype to be protective." (PMID 23083465, 2012). "To determine the consequences of En2 mutations on mouse behaviors, including outcomes potentially relevant to autism, we conducted comprehensive phenotyping of social, communication, repetitive, and cognitive behaviors." (PMID 22829897, 2012). "Original publications and replication studies have shown that SLC25A12 and EN2 are associated with autism." (PMID 20678243, 2010). "Considering EN2’s role in pattern formation during the central nervous system development, its decreased expression in the NSCs of patients with autism may underlie the disorganized colony formation of NSCs we observed in autism." (PMID 38994948, 2024). "En2 has been suggested to be an autism susceptibility gene and individuals with autism display an overexpression of this homeogene but the mechanisms remain unclear." (PMID 28809922, 2017). "The gene Engrailed 2 (En2) is located on chromosome 7 and has been linked to autism." (PMID 24151553, 2013). "Recent evidence indicates that EN2 is a risk gene for autism." (PMID 22829897, 2012). "Although the ASD-associated EN2 rs1861972-rs1861973 A–C haplotype conveys a gain of function, while deletion of En2 in mice conveys a loss of function, we detected striking social deficits in En2 knockouts in sociability tasks that incorporate conceptual analogies to the symptoms of autism." (PMID 22829897, 2012). "Similarly, in humans the engrailed homeobox 2 gene (EN2) has been associated with autistic disorder while the comparison to mouse En2 has genetic mutations involved in abnormal social integration, spatial learning, and social/consecutive interaction, among others." (PMID 20092628, 2010). "This is consistent with several previously published mouse models related to autism, including Chd8+/−, 22q11.2, Fmr1, Itgb3, En2, Nrxn1a, and Shank3." (PMID 33757588, 2021). "These commonly altered candidate genes were further compared with genes changed in the hippocampi of engrailed-2 (En2) mutant mice which show an autism-like phenotype." (PMID 30661326, 2018).
autism (continued). "The elevated En2 gene expression in the brain of individuals with autism prompted us to investigate the effects of an excess of En2 and, by comparison, of an excess of En1, on hippocampal cell morphology." (PMID 28809922, 2017). "Most of the assumptions about the role of En2 in autism have been discussed in relation with midbrain and posterior brain where it is highly expressed." (PMID 28809922, 2017). "While EN2 was expressed at higher levels in the post-mortem samples from individuals with autism, analysis of covariance for EN2 levels demonstrated a significant interaction between affection and genotype (p = 0.0006)." (PMID 24520327, 2014). "EN2 KO mice display social impairments which parallel symptoms of autism including decreased play, social behavior, and aggressive behavior as compared to controls." (PMID 23717269, 2013). "Increased neuronal packing, a smaller hippocampus, and ectopic location of neuronal subgroups in the amygdala in En2 KO mice also have been observed in autism postmortem brains." (PMID 24151553, 2013). "In this work NEMO was applied to a comparative study of neurons in culture obtained from labeled EN2+/− mice, an animal model of autism, and labeled WT mice." (PMID 23420185, 2013). "Engrailed 2 (EN2) [OMIM:131310], a Wnt target gene, has been associated with autism in several studies." (PMID 22050706, 2011). "By examining our expanded list of genes, we found several more of our connectivity linked genes are in AUTS1 and have been studied in the context of autism: Reln, Mest, Ptprz1, Dpp6 and En2." (PMID 21253556, 2011). "Previous studies have shown that variants in SLC25A12, EN2, ATP2B2 and PITX1, have an association with autism." (PMID 20678243, 2010). "EN2 knockout mice exhibit neuroanatomical and behavioral abnormalities that partly resemble those in patients with autism." (PMID 20678243, 2010). "It remains to be established whether En2 overexpressing mice display abnormal behaviors relevant to autism." (PMID 24355397, 2013). "Thus, EN2 KO mice also have cerebellar abnormalities that resemble those observed in autism such as hypoplasia, a reduction in the number of Purkinje cells by approximately 40%, and foliation defects." (PMID 23717269, 2013). "Face validity for the second and third diagnostic symptoms of autism, however, was not apparent in En2 nulls or heterozygotes." (PMID 22829897, 2012). "Investigations of subcellular localization of En2 within forebrain regions might shed light on its role in development of brain structures responsible for complex behaviors relevant to autism and other disorders." (PMID 22829897, 2012). "Our results suggest new directions for understanding the precise role of EN2 in elaborating neuroanatomical circuits during early brain development, which may contribute the symptoms of autism and other neurodevelopmental and psychiatric disorders." (PMID 22829897, 2012). "Knock-out mice, which lack both copies of EN2, display subtle cerebellar neuropathology and a behavior that could be interpreted as autism-like, for example, decreased play, reduced social sniffing and grooming, and reduced aggression." (PMID 23083465, 2012). "Our findings indicate a specific social deficit in En2 null mutants, recapitulating the first diagnostic symptom of autism, without abnormalities in the communication and repetitive symptom domains." (PMID 22829897, 2012). "Given the ASD-associated A–C haplotype functions as a transcriptional activator in cultured mouse neurons and human cell lines, the next important question is whether the A–C haplotype and affection status are correlated with altered EN2 expression in individuals with autism." (PMID 24520327, 2014). "Due to the observed similarities between autism improvements and the effects of exercise, we looked for genes changed by exercise in the SGZ and genes that are reversed in En2 knockout mice." (PMID 30661326, 2018).
autism (continued). "Some of these rodent models display both autism-like behavior and cerebellar pathology including the FMR1 knockout (KO) mouse, the engrailed homeobox 2 (EN2) KO mouse, and the staggerer mouse." (PMID 23717269, 2013). "Our findings, which confirm and extend previous reports, indicate the importance of En2 in regulation of social behaviors, cognitive abilities and motor functions in mice, the disruption of which may lead to behavioral phenotypes relevant to autism and related neuropsychiatric disorders." (PMID 22829897, 2012). "Moreover, the astrocytes of patients with autism exhibited higher expression of TGFB1 and TGFB2 but reduced expression of proliferator genes such as CXCR4 and NURR1 in addition to RELN, EN2, HAP1, SIRT1, and GPX1 vs. controls." (PMID 38994948, 2024). "Particularly interesting in the context of autism were the observations that En2, but not En1, can increase GABA cells complexity, and reduce the density of glutamatergic synapses." (PMID 28809922, 2017). "Consistent with this possibility, recent study demonstrated that human EN2 is epigenetically regulated and increased levels are observed in individuals with autism but these results were not correlated with the rs1861972-rs1861973 haplotype." (PMID 24520327, 2014). "The social deficits detected in En2 mutant mice provide face validity to the aberrant social interactions and lack of interest in others that are core features of autism, and may be relevant to other psychiatric disorders marked by social deficits, such as schizophrenia." (PMID 22829897, 2012).
prostate carcinoma (23 papers, 2008 to 2025). A carcinoma that arises from epithelial cells of the prostate gland. "We also provide evidence that down-regulation of EN2 expression causes a dramatic decrease in prostate cancer cell proliferation." (PMID 21566742, 2008). "Engrailed variant-2 (EN2) has been suggested as a potential diagnostic biomarker; however, its presence and functional role in prostate cancer (PCa) cells is still controversial or unknown." (PMID 31500112, 2019). "The EN2 protein content has been used as a urine detection indicator for early identification of prostate cancer through non-invasive testing, although its specificity is still controversial." (PMID 39607581, 2025). "Downregulating miR‐605 leads to a significant upregulation of the expression of EN2, promoting the proliferation and invasive capacity of prostate cancer cells." (PMID 40889210, 2025). "Several studies have confirmed that EN2 plays an important role in various malignant tumours, including colorectal cancer, prostate cancer, bladder cancer and gliomas." (PMID 40889210, 2025). "Several studies about human epithelial malignant tumors have also demonstrated high expression of the EN2 gene, such as prostate cancer, bladder cancer, ovarian cancer, and breast cancer." (PMID 39607581, 2025). "Here we applied the 3p3 immunoassay to the detection of urinary engrailed‐2 protein (EN2), a prostate cancer (PCa)‐specific marker." (PMID 37206218, 2023). "For prostate cancer, PSA, PCA3, GOLM1, and EN2 serve as valuable markers, highlighting diagnostic and prognostic potential." (PMID 38250812, 2023). "For instance, as a tumor-suppressor, lncRNA MEG3 binds to EZH2 resulting in H3K27-mediated trimethylation of Engrailed-2 (EN-2) to suppress prostate cancer progression." (PMID 35236381, 2022). "EN2 as a transcription factor was found to be a biomarker for prostate cancer and breast cancer in relevant studies." (PMID 36060650, 2022). "A recent meta-analysis evaluated the accuracy of EN2 protein in urine as a biological marker in prostate cancer, indicating that the urinary EN2 presented a high specificity (89%) and low sensitivity (66%)." (PMID 33350453, 2021). "In prostate cancer, EN2 facilitates cell cycle and multiplication of cancer cells through regulating PI3K/AKT pathway." (PMID 33685351, 2021). "This secretory behaviour of EN2 makes it a potential biomarker for prostate cancer, and indeed EN2 protein can be detected in the urine of men with prostate tumours." (PMID 33925381, 2021). "A study performed by Zhou et al23 demonstrated that overexpression of miR‐212 inhibited prostate cancer (PCa) cell proliferation and induced PCa cell apoptosis via targeting EN‐2, whereas the restoration of EN‐2 led to the opposite effect." (PMID 31930653, 2020). "Engrailed-2 (EN2) protein is found in the urine sample of prostatic cancer patients and showed a specificity of 88.2% and a sensitivity of 66%." (PMID 31508598, 2019). "Secretion of EN2 protein into the prostatic ductal lumen was also noted, prompting further investigation of EN2 as a biomarker in prostate cancer." (PMID 30285763, 2018). "EN2 was to be as the research object in our study in the light of its probable oncogenic role in breast cancer and prostate cancer." (PMID 24786097, 2014). "Here we demonstrated that EN2 is over-expressed in human prostate cancer cells compared to normal prostate epithelial cells." (PMID 21566742, 2008). "Here, we demonstrate that En-2 is over-expressed in human prostate cancer cells as compared to normal prostate epithelial cells." (PMID 21566742, 2008). "EN2 protein expressed and secreted through prostate cancer cells can be released into prostate cancer acini and catheters through prostate secretions; therefore, high concentrations of EN2 protein can be detected in the urine of prostate cancer patients." (PMID 39607581, 2025).
prostate carcinoma (continued). "Studies show that EN2 plays an important role in the proliferation, migration, and invasion of various tumor cells, including prostate cancer, colorectal cancer, esophageal squamous cell carcinoma, lung cancer, and bladder cancer, and is closely related to the poor prognosis of tumor patients." (PMID 36061185, 2022). "Indeed, a recent study indicated that prostate cancer cells can secrete EN2 protein through vesicles which are then taken up by other non-EN2 expressing cells, where it can directly influence the transcription of target genes." (PMID 33925381, 2021). "More recently, studies have demonstrated that EN2 also plays a role in prostate cancer and BC." (PMID 33350453, 2021). "Engrailed-2 (EN2) protein, a homeodomain-containing transcription factor expressed in prostate cancer and secreted into the urine, showed a highly specific and sensitive effect as a kind of biomarker for prostate cancer." (PMID 27594736, 2016). "QRT-PCR analysis of PAX2 was performed in LNCaP cells after treatment with EN2 siRNA to determine whether En-2 can modulate PAX2 expression in prostate cancer." (PMID 21566742, 2008). "Here we demonstrate that En-2 may contribute to the process of oncogenesis by conferring a growth advantage to prostate cancer cells by supporting cellular proliferation." (PMID 21566742, 2008). "Furthermore, EN2 is negatively regulated by miR‐605 in prostate cancer." (PMID 40889210, 2025). "However, EN2 was over-expressed in all of the prostate cancer cell lines." (PMID 21566742, 2008). "Therefore, our data suggests that EN2 is over-expressed in prostate cancer and may contribute to prostate tumorigenesis." (PMID 21566742, 2008). "Second, in migration and invasion of prostate cancer, lncRNA MEG3 suppresses Engrailed-2 (EN2) expression by inducing H3K27me3 on the EN2 promoter, which inhibits the cancer process." (PMID 33050646, 2020). "In the present work, we provide evidence that EN2 is aberrantly expressed in prostate cancer and is regulated by the PAX2 transcription factor that promotes prostate cancer cell growth and survival." (PMID 21566742, 2008). "EN2 expression was 8-fold higher in PC3 (lane 1), 6-fold higher in LNCaP (lane 2) and 4-fold higher in DU145 (lane 4) prostate cancer cells compared to hPrEC cells." (PMID 21566742, 2008). "Western Blot analysis was performed to monitor changes in EN2 protein levels after selective targeting and inhibition by En-2 specific siRNA in PC3 prostate cancer cells." (PMID 21566742, 2008). "Furthermore, MEG3 facilitates H3K27 trimethylation of EN2 through binding with EZH2, thus suppressing the development of prostate cancer." (PMID 33061817, 2020). "RT-QPCR revealed that promyelocytic leukemia derived HL60, melanoma derived SKMEL5, and the prostate cancer-derived cell lines DU145, PC3, and LNCaP, all express high levels of EN2, whilst WPMY-1 (a cell line derived from normal prostate fibroblasts) showed only very low levels of expression." (PMID 30914795, 2019). "Engrailed-2 (EN2) has been identified as a candidate oncogene in breast cancer and prostate cancer." (PMID 24786097, 2014). "Furthermore, we found a positive correlation between En-2 and PAX2 genes in prostate cancer cell lines, where cells exhibiting decreased EN2 expression also exhibited a down regulation of PAX2 expression level." (PMID 21566742, 2008). "Furthermore, we found a positive correlation between EN2 and PAX2 where prostate cancer cells exhibiting decreased EN2 expression also possessed decreased PAX2 levels." (PMID 21566742, 2008).